LEP (leptin)
Diseases named in the same sentence as LEP in open-access papers (continued):
Sharing a sentence is not in itself a finding about the gene and the disease.
psoriasis (continued). "Adipose tissue is a source of various proinflammatory cytokines, including adiponectin, leptin, resistin, TNF-α, and IL-6, participating in the pathogenesis of both psoriasis and non-alcoholic fatty liver disease (NFLD)." (PMID 41226807, 2025). "Over the one-year period, we observed a strong correlation between leptin and PASI scores, suggesting a role in the maintenance or even worsening of the chronic inflammation characteristic of psoriasis." (PMID 39767248, 2024). "In patients with psoriasis, there is an imbalance between the levels of pro- and anti-inflammatory adipokines (TNF-α, IL-6, leptin, resistin, and vifastin which increases, and adiponectin which decreases)." (PMID 38473907, 2024). "Leptin promotes IL-1, IL-6 and TNF-α production through its proinflammatory activity, which also affects psoriasis." (PMID 35216228, 2022). "In addition, leptin is an important signaling transducer which may link obesity and psoriasis." (PMID 34367173, 2021). "The excessive amount of adipose tissue is associated with decreased levels of anti-inflammatory adiponectin (ADIPOQ gene) and increased levels of pro-inflammatory leptin and leptin receptors (LEP, LEPR genes) in psoriasis." (PMID 34445769, 2021). "Due to its pro-inflammatory activity, leptin promoted production of IL-1, IL-6, and TNF-α, which also impacted the development and the severity of psoriasis." (PMID 33597945, 2020). "Leptin induces IL-6, CXCL-1, IL-8 and MCP-1 production, which is involved in the hyperproliferation of the epidermis in psoriasis." (PMID 32397568, 2020). "Due to its pro-inflammatory activity, leptin promoted IL-1, IL-6, chemokine 8 (CXCL8), and TNF-α production, which also impacts psoriasis." (PMID 33008429, 2020). "In conclusion, observed inflammatory and anti-inflammatory markers (CRP, adiponectin, leptin, resistin, and Lp-PLA2) are involved in both pathogenesis of MS and pathogenesis of psoriasis." (PMID 28097156, 2016). "When we compared the patients with psoriasis with the controls (before the therapy), we found significantly higher levels of proinflammatory markers (CRP and leptin) and insignificantly lower level of adiponectin." (PMID 26166954, 2015). "Leptin, an adipocyte-derived hormone, as an inflammatory mediator, stimulates the production of chemokines IL-1β and TNF-α from blood monocytes in obese patients with psoriasis." (PMID 39063202, 2024). "Leptin, as we have shown in our study, appears to be involved not only in metabolic health, but also in the pathophysiology of psoriasis, especially in those cases complicated by MS." (PMID 39767248, 2024). "For example, levels of leptin and resistin are elevated in obese individuals with psoriasis compared to those without the condition." (PMID 37047363, 2023). "Looking at the expression of leptin messenger (mRNA) in subcutaneous adipose tissue (SAT) in a group of obese and non‐obese psoriasis patients, the PASI score, serum leptin and expression of leptin mRNA in SAT was higher in the obese group compared to the non‐obese group." (PMID 37275420, 2023). "Then we analysed the correlations between plasma concentrations of adiponectin, leptin, and resistin, and parameters of psoriasis activity using the Dermatology Life Quality Index (DLQI), Psoriasis Activity Severity Index (PASI), and Body Surface Area (BSA) index." (PMID 36675592, 2023). "Another study with 47 psoriasis patients, serum levels of IL-6, TNF-α and proinflammatory adipocytokines (leptin, resistin and visfatin) were higher in psoriasis patients and serum adiponectin (an anti-inflammatory cytokine) was lower in psoriasis patients relative to healthy controls." (PMID 37681925, 2023). "Mean leptin concentrations were significantly higher (p < 0.05) in the study group than in subjects without psoriasis (428.61, 523.24, 755.27 and 154.10 pg/ml respectively)." (PMID 33927259, 2021).
psoriasis (continued). "The aim of the study was to investigate the influence of 36-month therapy with TNF-α inhibitors (adalimumab, etanercept, infliximab) on the levels of adipokines (resistin, adiponectin, leptin) and lipids (TG, cholesterol, LDL, HDL) in 37 psoriasis patients and 30 healthy controls." (PMID 33927259, 2021). "Importantly, SGs were found to express leptin, resistin, visfatin and SERPINE1 in lesional skin samples of patients with psoriasis." (PMID 33260746, 2020). "Furthermore, we also provided evidence to elucidate the complicated relationship between leptin and different dermatological diseases, such as systemic lupus erythematosus (SLE), psoriasis, hidradenitis suppurativa, and some skin tumors." (PMID 33597945, 2020). "Furthermore, we also provided evidence to elucidate the complicated relationship between leptin and different skin diseases, such as systemic lupus erythematosus (SLE), psoriasis, hidradenitis suppurativa, and some skin tumors." (PMID 33597945, 2020). "A recent meta-analysis showed that patients with psoriasis have higher levels of leptin compared to persons without psoriasis." (PMID 31417571, 2019). "In this sense, we have previously published that, in nondiabetic patients with moderate-to-severe psoriasis, leptin correlates with some metabolic syndrome features, whilst resistin correlates with inflammation and disease severity." (PMID 27293954, 2016). "In contrast, the concentrations of leptin and omentin in the erosive PsA patients, not in the non-erosive PsA patients, were higher than those in psoriasis controls." (PMID 23144698, 2012).
Infertility (107 papers, 2009 to 2025). "Humans and mice with loss-of-function mutations in nNOS (encoded by NOS1 and Nos1 genes, respectively) are infertile and global inhibition or deletion of NO production precludes leptin-induced LH secretion." (PMID 40276575, 2025). "Humans with a loss-of-function mutation in LEP gene are infertile, remaining in a prepubertal state unless leptin is replaced." (PMID 40276575, 2025). "Loss-of-function mutation in NOS1/Nos1 gene in humans and mice cause infertility and blockade of nitric oxide neurotransmission disrupts leptin actin in reproductive axis." (PMID 39007235, 2024). "This study provides a theoretical basis for the complex mechanisms underlying leptin, and infertility by employing leptin-overexpressing female pigs." (PMID 39227998, 2024). "Shreds of evidence from murine models has indicated that leptin deficiency leads to infertility, whereas exogenous administration of recombinant leptin restores fertility." (PMID 39227998, 2024). "The excess of leptin occurring during the eating disorders displaying overeating behaviors causes infertility, due to inhibiting follicle development." (PMID 39797110, 2024). "Fluctuations in leptin, the satiety hormone, affect hypothalamic–pituitary–ovarian axis function and ovarian follicle maturation, increasing the risk of infertility." (PMID 39797110, 2024). "Certain biomarkers in infertile patients, especially leptin, elevated in those presented with MetS and were associated with semen parameters." (PMID 39496062, 2024). "Consistent with this, ablation of these neurons or knockout of the genes encoding either neuropeptide or the NPY Y4 receptor partially rescues the infertility phenotype of leptin signalling‐deficient mice." (PMID 36306199, 2022). "Concerning the role of leptin in the ovary, evidence gathered from studies with leptin or ObR deficient mice, as well as women, confirmed their infertility and altered pubertal development." (PMID 33924072, 2021). "Polymorphisms rs7799039 and rs1137101 and circulating leptin and sOB-R levels were associated with infertility in Iranian women with PCOS." (PMID 34407095, 2021). "Next, we investigated glucose control mechanisms peculiar to the interstitium and tubules in the leptin-deficient (ob/ob) and leptin receptor-deficient (db/db) mice, two spontaneously diabetic and obese infertile type 2 diabetes mouse models." (PMID 32183843, 2020). "What is more, special attention should be paid to an explanation of the association of adiponectin, leptin, with infertility and BMI as it is still controversial." (PMID 32455738, 2020). "Leptin deficiency causes hypogonadotropic hypogonadism, low testicle weight, anestrus and infertility." (PMID 30694175, 2019). "Change in leptin levels can be considered as one of the factors responsible for causing infertility, as a result of its impact on estradiol (E2) production by human granulosa cells, in response to LH." (PMID 32025443, 2019). "Patients or rodents that are genetically lacking leptin or that harbor LepR mutations lack pubertal development and are infertile, with leptin replacement normalizing the reproductive axis in leptin-deficient subjects." (PMID 29706935, 2018). "Leptin-deficient ob/ob mice exhibited disturbances of puberty and infertility, and chronic leptin treatment increased the serum gonadotropin level and restored puberty and fertility in mice." (PMID 29976877, 2018). "Last decades, particular attention was paid to the effect of leptin on reproduction, especially on the gonadal dysfunction as infertility, a characteristic feature of both ob/ob (leptin deficient) and db/db (leptin receptor mutant) mice." (PMID 23803253, 2013). "Studies from two independent laboratories have demonstrated that ablation of AgRP neurons or knockout of one allele of Mc4r gene corrected the infertility phenotype of leptin-signaling-deficient mice." (PMID 22851226, 2013).
Infertility (continued). "Some previous studies have investigated the association between leptin, infertility, and chronic pelvic pain." (PMID 23634146, 2013). "The infertility phenotype observed in leptin-deficient mice is dependent on genetic background, as obese ob/ob mice crossed onto a BALB/cJ strain have improved fertility." (PMID 22851226, 2013). "A role for leptin on the onset of puberty is evident in leptin-deficient ob/ob mice, which have arrested puberty and infertility." (PMID 23248615, 2012). "However, our findings suggest an association between leptin concentration and endometriosis-associated infertility, albeit based on a limited number of samples." (PMID 38567305, 2024). "The results were in line with the phenotype observed in leptin pigs, suggesting disrupted hormone homeostasis and providing insights into the mechanisms underlying infertility in leptin pigs, particularly concerning cholesterol biosynthesis, granulosa cell function, and apoptosis regulation." (PMID 39227998, 2024). "Mice deficient for leptin (ob/ob) or the leptin receptor (db/db) are infertile." (PMID 36138127, 2022). "Moreover, in this research study, we evaluated for the first time the association of sOB-R and leptin levels, and these two single nucleotide polymorphisms with infertility and RPL in PCOS patients." (PMID 34407095, 2021). "Higher leptin levels are considered to be the cause of infertility." (PMID 32025443, 2019). "Leptin deficient mice were described to have high rates of insulin resistance and infertility." (PMID 28409493, 2017). "BMI and IR have positive association with serum leptin in PCOS infertile women." (PMID 29177243, 2017). "Itis believed that leptin deficiency can be an independent cause of infertility inthese women." (PMID 28050960, 2016). "Thus, altered leptin signalling and associated impaired mitochondrial function most certainly affect the oocyte quality and contributes to the pathogenesis of ovarian failure and infertility in maternal obesity." (PMID 36855701, 2022). "Moreover, higher LEP levels may be correlated with insulin receptor, metabolic disorder, infertility, and even cardiovascular disease risk in PCOS, which may contribute to the etiology and development of PCOS." (PMID 29430464, 2017). "Impaired function and/or reduced levels of leptin might thus cause infertility in women with PCOS." (PMID 24895638, 2014). "BMI, glucose, TG, follicle-stimulating hormone (FSH), and leptin were significantly higher in MetS infertile patients (P < .001; P < .005; P < .001; P < .001; and P < .001, respectively)." (PMID 39496062, 2024). "The objective of this study was to assess the serum leptin levels in Chinese patients and determine the relationships between these levels and MetS and semen parameters in infertile patients." (PMID 39496062, 2024). "In this study, we assessed the relationships between serum biomarkers and semen parameters in patients with infertility, according to the presence of MetS comparing with the HCs, and the significance of serum leptin level in the correlation with semen quality." (PMID 39496062, 2024). "We found that infertile patients with higher leptin levels had lower progressive motility, which is in accordance with other studies." (PMID 39496062, 2024). "This study investigates links between CART and leptin gene expression, FSH receptor Asn680Ser polymorphism, and reproductive hormones in morbidly obese patients under 40 years old, facing infertility, and undergoing bariatric surgery." (PMID 38673534, 2024). "Leptin resistance reduces the ability of the endometrium to respond to these signals, potentially leading to implantation failure and infertility." (PMID 39767708, 2024). "BMI, glucose, triglyceride, FSH, and leptin were significantly higher in MetS infertile patients (P = .001; P = .005; P < .001; P = .001; and P < .001, respectively)." (PMID 39496062, 2024).
Infertility (continued). "To further dissect the mechanism for high leptin-induced infertility, we compared all cells of the leptin group and WT group and chose the top 400 DEGs to perform GO analysis." (PMID 39227998, 2024). "A future attempt should be made to study extensively the polymorphisms of the FSHR gene and to correlate them with CART and leptin gene expression and with the hormonal profile of obese women suffering from infertility." (PMID 38673534, 2024). "Elevated levels of leptin have been observed in obese infertile male individuals with disorders affecting the parenchyma of the testicles, such as nonobstructive azoospermia and oligozoospermia." (PMID 38203349, 2023). "Li and colleagues reported that leptin levels in the FF of infertile women with PCOS was higher when compared to those of women without PCOS." (PMID 37493841, 2023). "Evidence that leptin promotes the onset of labor includes a study in thethe Lepob/ob mouse, which cannot produce leptin, and is infertile." (PMID 36163455, 2022). "Leptin is essential for some reproductive functions, with leptin injections improving the likelihood of conception in infertile mice and leptin initiating the onset of puberty in human females." (PMID 35348641, 2022). "In our study, serum leptin levels were measured in normal and infertile male subjects with different categories of infertile patients." (PMID 36213199, 2022). "Leptin‐deficient ob/ob mice exhibit disturbed sexual maturation and infertility due to low gonadotrophin levels, and chronic leptin treatment increased their serum gonadotrophin levels and restored puberty and fertility." (PMID 34934398, 2022). "The result denoted that serum or seminal leptin in infertile males was higher than that in normal fertile men." (PMID 36213199, 2022). "The serum or seminal leptin levels slightly differed between the infertile male patients and fertile ones in subgroup analyses." (PMID 36213199, 2022). "LEP (rs7799039) and LEPR (rs1137101) polymorphisms and the risk of PCOS, PCOS-infertile, and PCOS-RPL." (PMID 34407095, 2021). "In line with our data, the results of a study by Jahromi et.al showed that infertile women with PCOS had an increased level of leptin as compared to the control group." (PMID 34407095, 2021). "Leptin also plays some important roles during pregnancy—recombinant leptin improved conception in infertile mice, whilst regulatory roles in immunomodulation, angiogenesis and nutrient transport have been described in the placenta." (PMID 34729242, 2021). "Mice lacking leptin (ob/ob) or leptin receptor (db/db) are both obese and infertile, and leptin administration to ob/ob mice normalizes food intake, body weight and hypogonadism." (PMID 33573212, 2021). "According to the results of this study and other research, it can be assumed that the association of LEP and LEPR variants with PCOS–and also PCOS-related infertility and RPL- is dependent on the ethnic/racial background of the study population." (PMID 34407095, 2021). "Statistically significant correlations between serum reproductive hormones, lipids and leptin also existed in Chinese infertile men." (PMID 32993674, 2020). "In the preovulatory phase (12th day) of the cycle, infertile subjects with BMI <20 and 20-24.9 had significantly higher values for leptin (p<0.05) as compared to the fertile ones." (PMID 32025443, 2019). "The low E2 in infertile females correlated with slightly raised leptin levels in low BMI females and reduced leptin levels in high BMI females of UI." (PMID 32025443, 2019). "The increase in serum leptin during the luteal phase of the cycle in both fertile and infertile women having normal weight was observed in our study that has been reported by others." (PMID 32025443, 2019).